GNRHR (gonadotropin releasing hormone receptor)
Diseases named in the same sentence as GNRHR in open-access papers (continued):
Sharing a sentence is not in itself a finding about the gene and the disease.
hyperandrogenism (4 papers, 2019 to 2025). Excessive secretion of androgens from the adrenal glands or gonads. "Secondly, given the interplay between androgens, adipose tissue, and inflammation in PCOS, GnRHR autoantibodies may exacerbate inflammation by disrupting adipokine balance through hyperandrogenism." (PMID 40362363, 2025). "Taken together, elevated GnRHR‐AAb enhanced LH, hyperandrogenism, and inflammation." (PMID 33356018, 2021). "Pathophysiological functions of genes are primarily responsible for the synthesis of proteins that have role in PCOS before hyperandrogenism including GnRHR, FSHβ, FSHR, LHCGR, CYP19A1, HSD17B, AR and SHBG, and their effects in PCOS of human have been confirmed." (PMID 30944702, 2019).
lymph node metastasis (4 papers, 2012 to 2025). "Strong IL23R expression and the translocation of beta-catenin, regulated by the GnRH/GnRHR pathway, were seen in some of the patient samples and correlated with signs of poor prognosis, namely Dukes' staging and the presence of lymph node metastasis." (PMID 22173670, 2012). "In addition, GnRHR expression is also detected in lymph node metastasis." (PMID 32185134, 2020). "Strikingly, GnRHR-negative tumors were strongly correlated with FIGO progression, lymph node metastasis, and distant dissemination, further reinforcing its role as a predictor of clinical outcomes." (PMID 41458598, 2025).
Autoimmunity (3 papers, 2021 to 2025). The occurrence of an immune reaction against the organism's own cells or tissues. "An autoimmune PCOS model was successfully developed by immunizing rats with a synthetic peptide derived from the GnRHR-ECL2 sequence—identical to the epitope targeted by GnRHR autoantibodies in humans with PCOS." (PMID 40362363, 2025).
diabetes (3 papers, 2014 to 2024). "Interestingly, diabetes-related pathways regulation of insulin secretion (R-HSA-422356), and integration of energy metabolism (R-HSA-163685), as well as puberty-related gonadotropin-releasing hormone receptor pathway (P06664), were enriched." (PMID 38775154, 2024).
hypothyroidism (3 papers, 2017 to 2021). Abnormally low levels of thyroid hormone. "The association of miRNA-938 with GnRHR expression can be considered in the context of the association between GnRH agonists and hypothyroidism." (PMID 34200157, 2021). "The association of miR-938 with GnRHR expression should also be considered in the context of the association of GnRH agonists with hypothyroidism." (PMID 28604625, 2017). "We were therefore unable to determine whether hypothyroidism affects the distribution of GnRHR in the nuclei of the ovary." (PMID 29793475, 2018). "Because THs may act as potential mediators of GnRH neurons, hypothyroidism may affect the distribution of the pituitary GnRHR." (PMID 29793475, 2018). "Our studies in SD rats indicated that hypothyroidism may affect the allocation of the pituitary GnRHR; however, whether THs play a role in the ovaries and hypothalamus and the nature of their involvement remains unclear, and there are few relevant reports in the literature." (PMID 29793475, 2018). "The present results suggested that hypothyroidism affects the distribution of the pituitary GnRHR; however, we observed no evident effect on the distribution of the GnRHR of the ovary and hypothalamus." (PMID 29793475, 2018). "Hypothyroidism had an adverse impact on pregnancy in rats and may affect the distribution of pituitary GnRHR, whereas it did not obviously affect the distribution of GnRHR in the nuclei of the hypothalamus and ovary." (PMID 29793475, 2018).
Insulin resistance (3 papers, 2021 to 2025). Increased resistance towards insulin, that is, diminished effectiveness of insulin in reducing blood glucose levels. "The increased GnRHR‐AAb and testosterone were associated with the induced insulin resistance and impaired insulin response to a glucose challenge." (PMID 33356018, 2021). "In summary, we have provided evidence that GnRHR‐AAb induces insulin resistance in peripheral tissue early during the development of several manifestations of a PCOS‐like phenotype." (PMID 33356018, 2021). "The results demonstrated that immune and inflammatory elements serve as critical components in GnRHR‐AAb‐induced peripheral insulin resistance." (PMID 33356018, 2021). "Our experiment indicated that GnRHR‐AAb may induce an imbalance between pro‐ and anti‐inflammatory cytokines and thereby enhance peripheral insulin resistance." (PMID 33356018, 2021). "It is unclear whether GnRHR‐AAb can induce peripheral tissue insulin resistance (IR) in animal models." (PMID 33356018, 2021). "This indicated that inflammation may play an important role in the insulin resistance induced by the GnRHR‐AAb." (PMID 33356018, 2021). "These GnRHR IMM rats appear to share several features, including insulin resistance, with human PCOS." (PMID 33356018, 2021). "All of these changes suggested that elevated GnRHR‐AAb induced glucose intolerance and insulin resistance, which was independent of the body weight and fasting blood glucose." (PMID 33356018, 2021). "Even after a relatively short period of GnRHR‐AAb stimulation (20 w), the IMM rats showed glucose intolerance and insulin resistance independent of body weight and fasting blood glucose." (PMID 33356018, 2021).
myocardial infarction (3 papers, 2020 to 2024). Gross necrosis of the myocardium, as a result of interruption of the blood supply to the area, as in coronary thrombosis. "Analysis of questionnaire data relating to puberty and fertility, genotyping of the GNRHR p.Q106R variant, and hormone profiling of a highly phenotyped Maltese adult cohort from the Maltese Acute Myocardial Infarction Study." (PMID 38196663, 2024).
Primary amenorrhea (3 papers, 2017 to 2021). "The two anosmic KS females with a history of primary amenorrhea harbored P/LP variants (in the first case in the GNRH1 gene (with no other accompanying congenital defect), and in the second case in the GNRHR gene), presenting incomplete rotation of the right kidney." (PMID 34198905, 2021).
adenoma (2 papers, 2016 to 2017). A neoplasm arising from the epithelium. "Multiple regression analysis revealed that the presence of the KCNJ5 mutation was negatively linked to GNRHR mRNA expression levels following adjustment for gender, age, serum potassium levels, and adenoma diameter." (PMID 27196470, 2016). "GnRHR showed diffuse cytoplasmic, membranous and nuclear expressions on adenomas, and was especially enhanced in adenoma harboring CTNNB1 mutations from female patients." (PMID 28102204, 2017). "In APA-WT, GNRHR expression in adenomas might participate in the regulation of aldosterone production." (PMID 27196470, 2016). "We postulate that in adenomas with no somatic mutations of the KCNJ5 gene, that aberrant GNRHR expression regulates aldosterone production." (PMID 27196470, 2016). "Multiple regression analysis revealed a significant correlation between aldosterone increase and GNRHR mRNA levels that was independent of age, gender, serum potassium levels, and adenoma diameter (β = 0.242 and P < 0.01)." (PMID 27196470, 2016).
adrenal adenomas (2 papers, 2019 to 2023). "This original case was followed by the description of 3 cases with primary hyperaldosteronism during pregnancy (n=2) and menopause (n=1), showing LHCGR and GnRHR overexpression in adrenal adenomas by microarray analysis and qPCR." (PMID 36926028, 2023). "LH/HCG GPCR (LHCGR) and GnRHR can also be ectopically expressed in adrenal adenomas or adrenal hyperplasia leading to hyperaldosteronism." (PMID 36926028, 2023). "GNRHR expression has also been found in adrenocortical adenomas producing aldosterone." (PMID 30400009, 2019). "Previously, GNRHR localization was shown in normal adrenal glands (medulla and cortex), adrenocortical adenomas and in the SW13 adrenocortical cell line, but never in adrenocortical carcinomas." (PMID 30400009, 2019).
colon adenocarcinoma (2 papers, 2017 to 2025). "We co-transfected a GnRHR expression construct along with the reporter gene construct containing either the A or G allele of miR-938 of rs12416605 into human granulosa (KGN), endometrial adenocarcinoma (Ishikawa and SNU-539) and colon adenocarcinoma (Caco-2) cells." (PMID 28604625, 2017).
colorectal cancer (2 papers, 2024 to 2025). A primary or metastatic malignant neoplasm that affects the colon or rectum. "We apply our method to a large study of colorectal cancer to identify a significant pPRS x NSAIDs interaction (p = 0.0003) based on SNPs within the TGF-β/ gonadotropin releasing hormone receptor (GRHR) pathway." (PMID 40763299, 2025). "We apply our method to a large study of colorectal cancer to identify a significant pPRS × NSAIDs interaction (p=0.0003) based on SNPs within the TGF-β / gonadotropin releasing hormone receptor (GRHR) pathway." (PMID 39763728, 2024).
Delayed puberty (2 papers, 2019 to 2020). Passing the age when puberty normally occurs with no physical or hormonal signs of the onset of puberty. "As loss-of-function mutations within the GnRH receptor are one of the most frequent causes of CHH, the GNRHR gene has been repeatedly sequenced in patients with self-limited delayed puberty." (PMID 31220230, 2019).
neuroblastoma (2 papers, 2011 to 2019). Neuroblastoma (NB) is the most common solid, extracranial childhood tumor. "GnRH receptor (GnRHR)-transfected HEK293 and neuroblastoma-derived SH-SY5Y cell lines, as well as mouse pituitary LβT2 cells endogenously expressing the murine GnRHR, were treated with GnRH in the presence or absence of the antagonist." (PMID 31703269, 2019).
5-alpha-reductase deficiency (1 paper, 2017). "These include three patients (i.e., P09, P22, P28) with 5-alpha-reductase deficiency due to biallelic mutations of the SRD5A2 gene, and four patients with idiopathic hypogonadotropic hypogonadism due to mutations of KAL1 (i.e., P27, P32), PROKR2 (P03) or GNRHR (P13)." (PMID 28295047, 2017).
acromegaly (1 paper, 2024). Acromegaly is an acquired disorder related to excessive production of growth hormone (GH) and characterized by progressive somatic disfigurement (mainly involving the face and extremities) and systemic manifestations. "Moreover, pituitary tumors of LHRH responders in acromegaly might express gonadotropin-releasing hormone receptor (GnRHR) and gonadotropin." (PMID 38954291, 2024). "Therefore, the increased GH response to LHRH stimulation in acromegaly could partly depend on GnRHR." (PMID 38954291, 2024).
adrenal tumor (1 paper, 2019). "It would be interesting to validate the LH dependency of the tumor progression and the expression of GNRHR in the ferret adrenal tumor tissues, as they could serve as another model for adrenocortical carcinomas." (PMID 30400009, 2019).
adrenocortical carcinomas (1 paper, 2019). "In situ hybridization and qPCR analysis of human adrenocortical carcinomas (n = 11–13) showed expression of GNRHR in 54/73%, LHCGR in 77/100% and FSHR in 0%, respectively." (PMID 30400009, 2019). "To confirm that the effect of CTX on adrenocortical carcinoma cells acts through GNRHR, we performed siRNA-mediated GNRHR knockdown in human H295R cells." (PMID 30400009, 2019). "We found that human adrenocortical carcinomas and mouse adrenocortical tumors expressed GNRHR and LHCGR mRNA and protein at variable levels, probably due to the well-known high heterogeneity of the tumors." (PMID 30400009, 2019). "In order to assess whether the adrenocortical carcinoma samples express GNRHR, LHCGR and FSH expression was studied using a commercial in situ hybridization RNAscope kit with single transcript resolution." (PMID 30400009, 2019). "Our data suggest that CTX treatment may improve the therapy of human adrenocortical carcinomas by direct action on GNRHR-positive cancer cells inducing apoptosis and/or reducing gonadotropin release, directing tumor cells towards a healthy adrenal gene expression profile." (PMID 30400009, 2019). "We analyzed the expressions of receptors of gonadotropin-releasing hormone (GNRHR), luteinizing hormone/chorionic gonadotropin (LHCGR) and follicle-stimulating hormone (FSHR) in human adrenocortical carcinomas and assessed their response to GnRH antagonist therapy." (PMID 30400009, 2019).
amenorrhea (1 paper, 2017). The absence of menses in a woman who has achieved reproductive age. "We examined adolescents and young adults with stalled puberty or unexplained amenorrhea for mutations in GNRHR, FGFR1, TAC3, and TACR3 genes." (PMID 29182666, 2017).
cervical cancer (1 paper, 2017). A primary or metastatic malignant neoplasm involving the cervix. "Intriguingly, GnRHR antagonists appear to be less cytotoxic and more potent in mouse models of cervical cancer compared to GnRHR agonists." (PMID 28439256, 2017).
congenital adrenal hyperplasia (1 paper, 2023). Congenital adrenal hyperplasia (CAH) is an inherited endocrine disorder caused by a steroidogenic enzyme deficiency that is characterized by adrenal insufficiency and variable degrees of hyper or hypo androgyny manifestations, depending of the type and the severity of the disease. "The pathophysiology of GnRHR makes it a potential target for treatments in several reproductive diseases and in congenital adrenal hyperplasia." (PMID 37958948, 2023).
depression (1 paper, 2026). "And we found that both GnRH and GnRHR were down-regulated in the anterior cingulate cortex of mice that were subjected to chronic pain-induced depression with complete Freund's adjuvant." (PMID 42063519, 2026). "Specifically, either systemic treatment with GnRH agonists or GnRH overexpression in the anterior cingulate cortex effectively ameliorated the chronic pain-induced depression-like behaviour via GnRHR signalling." (PMID 42063519, 2026). "Therefore, our findings indicate that GnRH/GnRHR is involved in the development of chronic pain-related depression, which may through rebalancing the excitatory-inhibitory neurons via the activation of protein kinase C/Erb-B2 receptor tyrosine kinase 4 pathway." (PMID 42063519, 2026).
dermatitis (1 paper, 2023). An inflammatory process affecting the skin. "We sought literature support for the DT, Gonadotropin-releasing hormone receptor (GNRHR), and the level 2 ATC code D07, both of which had positive coefficients for predicting the side effect of dermatitis." (PMID 40980115, 2023).
Gonadotropin deficiency (1 paper, 2017). A reduced ability to secrete gonadotropins, which are protein hormones secreted by gonadotrope cells of the anterior pituitary gland, including the hormones follitropin (FSH) and luteinizing hormone (LH). "Clinical characteristics and GNRHR genotypes in adolescent and young adult females with clinical and biochemical findings suggesting partial gonadotropin deficiency." (PMID 29182666, 2017).
Graves disease (1 paper, 2025). Graves' disease is an autoimmune disorder that leads to overactivity of the thyroid gland (hyperthyroidism).It is caused by an abnormal immune system response that causes the thyroid gland to produce too much thyroid hormones. "Anti-GnRHR antibodies appear particularly intriguing, as they have been demonstrated to target the second extracellular loop (ECL2) of the gonadotropin-releasing hormone receptor and act similarly to activating anti-TSHR antibodies in Graves’ disease." (PMID 40943118, 2025).
head and neck cancer (1 paper, 2019). A primary or metastatic malignant neoplasm affecting the head and neck. "Gonadotropin-releasing hormone receptor (GnRH-R) expression is less studied in head and neck cancers, hence, we investigated the therapeutic relevance of GnRH-R targeting in HNSCC patients." (PMID 31614426, 2019).
invasive breast carcinoma (1 paper, 2009). A carcinoma that infiltrates the breast parenchyma. "We sequenced exons of GNRH1 and GNRHR in 95 invasive breast cancer cases." (PMID 19640273, 2009).
osteoporosis (1 paper, 2024). A condition of reduced bone mass, with decreased cortical thickness and a decrease in the number and size of the trabeculae of cancellous bone (but normal chemical composition), resulting in increased fracture incidence. "The activation of the GnRHR would, in turn, induce an increase in the synthesis of estrogen in the ovary by the hypothalamic–pituitary–gonadal axis and based on estrogen’s association with osteoporosis, we initiated a study on the potential of GV1001 as a treatment for osteoporosis." (PMID 39062525, 2024).
osteosarcoma (1 paper, 2019). A usually aggressive malignant bone-forming mesenchymal neoplasm, predominantly affecting adolescents and young adults. "Pro-proliferative effects were reversed by treatment with GnRHR and 5HTR2A antagonists, suggesting that these neuroendocrine hormones should be included in a list of viable targets for the treatment of osteosarcoma." (PMID 30777054, 2019). "Additionally, while we observed effects of GnRH in osteosarcoma cell lines in the form of changes in proliferation and gene expression, the pituitary-typical transcript of GnRHR was found to have a significantly low basal abundance in COS cells." (PMID 30777054, 2019).
Ovarian cyst (1 paper, 2023). The presence of one or more cysts of the ovary. "Variants in genes GNRH1 and GNRHR genes have also been identified in a 6.5-year-old girl with ovarian-cyst-derived peripheral precocious puberty." (PMID 36980008, 2023).
pituitary deficiency (1 paper, 2016). "In turn, that means that second allele of GNRHR in Patient 1 genome remains mutation free, and that one copy of wild type allele able to compensate for the deficiency of the receptor for GnRH binding only partially, at least in presence of pituitary deficiency and/or GnRH1 variant." (PMID 27544332, 2016).
pituitary tumor (1 paper, 2024). A benign or malignant neoplasm affecting the pituitary gland. "We demonstrated that the LHRH responders had a higher frequency of pituitary tumors positive for SF-1, GnRHR, and LH." (PMID 38954291, 2024). "In addition, a high proportion of GnRHR expressing pituitary tumor was found in LHRH responders than in LHRH nonresponders." (PMID 38954291, 2024). "In addition, a greater increased rate of GH after LHRH loading, and the proportion of GnRHR and gonadotropin expression was observed in pituitary tumor with SF-1 expression than that without the expression (P < 0.01)." (PMID 38954291, 2024).
primary aldosteronism (1 paper, 2023). An endocrine disorder characterized by excessive production of aldosterone by the adrenal glands. "The involvement of somatic CTNNB1 mutations in the induction of LHCGR and GnRHR ectopic expression and pregnancy-LH/HCG stimulated primary aldosteronism has been questioned." (PMID 36926028, 2023).
scrub typhus (1 paper, 2021). Scrub typhus is a rare dust mite-borne infectious disease caused by the Orientia tsutsugamushi bacterium and characterized clinically by an eruptive fever which is potentially serious. "Since epidemiological studies reported that the susceptibility of women to scrub typhus was higher than that of men, further research investigating the association between susceptibility according to sex and the gonadotropin-releasing hormone receptor pathway is warranted." (PMID 33807835, 2021).
serous ovarian carcinomas (1 paper, 2020). "GnRHR expression was confirmed by IHC analysis of 56 high-grade serous ovarian carcinomas from our tissue bank." (PMID 32185134, 2020). "Consistent with previous studies, our own analysis confirmed that the majority (95%) of high-grade serous ovarian cancers express moderate to high levels of GnRHR." (PMID 32185134, 2020).
somatotropinoma (1 paper, 2018). "In contrast, other receptors subtypes involved in the function of different pituitary cell types, such as gonadotropin-releasing hormone receptor (GnRHR), corticotropin-releasing hormone receptor (CRHR1) or vasopressin receptor (AVPR1b) were not noticeably expressed in somatotropinoma samples." (PMID 29670116, 2018).